RN7SL401P (RNA, 7SL, cytoplasmic 401, pseudogene)
Gene: Miscellaneous RNA gene on chromosome 18 (73,744,935 to 73,745,232, forward strand). Ensembl gene ENSG00000241866.
Homologues: Orthologues: chimpanzee Metazoa_SRP (98% identical), macaque Metazoa_SRP (91% identical). Paralogues in human: RN7SL1 (80% identical), RN7SL709P (79% identical), RN7SL3 (79% identical), RN7SL2 (79% identical), RN7SL220P (79% identical), RN7SL655P (78% identical), RN7SL478P (78% identical), RN7SL125P (77% identical), RN7SL448P (77% identical), RN7SL543P (77% identical), RN7SL556P (77% identical), RN7SL597P (77% identical), and 703 more.